SPEN (spen family transcriptional repressor)
Diseases named in the same sentence as SPEN in open-access papers (continued):
Sharing a sentence is not in itself a finding about the gene and the disease.
tumor (continued). "CDKN2A/B co‐mutations were significantly represented in tumours with STK11 (63%, 10/16, p = 0.024), KEAP1 (59%, 10/17, p = 0.045), and SPEN (90%, 9/10, p < 0.001) alterations, and in all tumours with MTAP alterations (100%, 16/16, p < 0.001)." (PMID 41015991, 2025). "Regarding the down-regulated genes, SPEN, a transcriptional repressor, has been identified as a tumor suppressor that is able to regulate cell proliferation, tumor growth, and survival in hormone-dependent breast cancers." (PMID 38918490, 2024). "In conclusion, our study determined the expression of SPEN was significantly different in various cancers from the TCGA cohort and clinical tumor samples." (PMID 37620924, 2023). "Here, we show that split end (SPEN), a transcription repressor, coordinates rRNA synthesis in endothelial cells (ECs) and is required for physiological and tumor angiogenesis." (PMID 37607001, 2023). "Activated TECs upregulate their SPEN to facilitate rRNA gene transcription by repressing pRNA, and SPEN is therefore required for tumor angiogenesis." (PMID 37607001, 2023). "The results showed that endothelial SPEN deficiency markedly enhanced the efficacy of CDDP, as shown by reduced tumor growth and increased tumor tissue necrosis." (PMID 37607001, 2023). "The truncal location of SPEN alterations in three different cases suggests this is a bona fide tumour suppressor and mediator of resistance to endocrine therapy." (PMID 28027312, 2016). "Therefore, high endothelial SPEN level positively correlates with tumor progression in both human and mouse models." (PMID 37607001, 2023). "Furthermore, SPEN mutation was significantly correlated with tumor-infiltrating lymphocytes, immunoinhibitors, immunostimulators, MHC, chemokines, and chemokine receptors, and SPEN expression was positively correlated with immune checkpoint genes." (PMID 37620924, 2023). "The representative IHC images of SPEN expression in tumor and normal tissue were shown." (PMID 37620924, 2023). "Greater tumour size reductions at best response were observed in patients with baseline SPEN mutations compared to those without (p = 0.048)." (PMID 36583171, 2022). "SPEN has been reported to play a dual role in tumor development." (PMID 32641685, 2020). "F-box/WD repeat-containing protein 7, FBXW7, mediator complex subunit 12 (MED12), and spen family transcriptional repressor (SPEN), three tumor suppressors associated with the regulation of the NOTCH1 pathway, were also identified as being mutated with low frequency in CLL." (PMID 32182763, 2020). "The data revealed that miR-4652-3p was a significantly positive-regulator of SPEN and might function as a tumor-promoted role in NPC cells." (PMID 32641685, 2020). "SPEN mutations have also been associated with resistance to NOTCH pathway-targeted therapies, suggesting that SPEN mutations may contribute to therapeutic resistance and tumor progression." (PMID 39199639, 2024). "Together, these results demonstrate that SPEN is required for angiogenesis by repressing pRNA to enable rRNA gene transcription and ribosomal biogenesis and that RNPI represents a target for tumor vessel normalization therapy of cancer." (PMID 37607001, 2023).
tumor (continued). "For example, gene SPEN is detected by our model from BRCA dataset, which is reported to be capable of regulating tumor growth and cell proliferation." (PMID 29871594, 2018). "In addition, survival-related AS events might be involved in tumor-related pathways including base excision repair and pyrimidine metabolism pathways, and some splicing factors might be correlated with prognosis-related AS events, including SPEN, SF3B5, RNPC3, LUC7L3, SRSF11 and PRPF38B." (PMID 34001978, 2021). "Several outlier genes whose knockdown confers striking vulnerability are tumor suppressors including APC, PHLPP1 and SPEN, while a number of other candidates have been reported to harbor anti-oncogenic activities such as the pro-apoptotic gene MTCH2 and the anti-metastatic RNA chaperone RBM47." (PMID 27296290, 2016). "Interestingly, some of them function as tumor suppressors (e.g. BCL2L11, MXD1, WWOX, BNIP3L, and DMTF1) or are candidate tumor suppressors having anti-proliferative properties and DNA repair abilities (e.g. LRRC2, RPA4, PPP6R1, SPEN, RAP1GAP and CISH) (see discussion section)." (PMID 26918450, 2016).
cancer (27 papers, 2013 to 2024). A tumor composed of atypical neoplastic, often pleomorphic cells that invade other tissues. "SPEN mutations’ influence extends beyond the realm of CRCs, as evident through its participation in various cancer-related pathways observed within other malignancies." (PMID 38392565, 2024). "The results suggested that SPEN expression was significantly associated with MMR genes in almost all cancer." (PMID 37620924, 2023). "Intriguingly, we found that SPEN mutation indicated better prognostic values, and also served as a strong prognostic factor for cancer patients treated with ICI therapy." (PMID 37620924, 2023). "In the future, a prospective study with a larger sample size of cancer patients treated with ICI is warranted to explore the predictive value of SPEN mutation." (PMID 37620924, 2023). "A positive association between SPEN and these genes in the majority of detailed cancer type was observed in the heatmap." (PMID 37620924, 2023). "Furthermore, an association between SPEN’s function and multiple cancer-related pathways—including WNT signaling plus NOTCH circuits— both crucial to the carcinogenesis of CRC, has been established." (PMID 38392565, 2024). "Furthermore, the study investigated a correlation between SPEN mutations and clinical characteristics, uncovering a significant link with the primary stage of cancer as classified by the AJCC." (PMID 38392565, 2024). "However, a significant association was found with cancer stage in the TCGA cohort, particularly at stage II, indicating a potential relationship between SPEN mutation status and cancer progression." (PMID 38392565, 2024). "Our findings demonstrated that SPEN mutation might strongly predict immunotherapy efficacy in pan-cancer." (PMID 37620924, 2023). "Thus, we aimed to investigate the association between SPEN mutation and the prognosis and immunotherapy in human cancer." (PMID 37620924, 2023). "To evaluate whether SPEN mutation is a predictive biomarker for cancer immunotherapy, we analyze the data, including 2,938 patients from 9 studies that receive ICIs treatment." (PMID 37620924, 2023). "In addition, SPEN mutation was an independent biomarker after adjusting for confounding factors, including age, cancer type, treatment strategy, and TMB." (PMID 37620924, 2023). "Primarily engaged in X chromosome silencing (XCI), SPEN has a critical function in tumorigenesis and gender disparities within cancer." (PMID 38392565, 2024). "Through both bioinformatics analysis and immunohistochemical staining, it has been substantiated that there is indeed significant variation in SPEN expression across diverse forms of cancers." (PMID 38392565, 2024). "SPEN is a transcriptional regulator that plays a role in development, differentiation, and cancer progression." (PMID 37960940, 2023). "Our results suggested that abnormal SPEN expression related to prognostic values in some cancer types." (PMID 37620924, 2023). "It was worth noting that SPEN expression was negatively correlated with infiltration level of NKT and T-helper 1 (Th1) cells and positively correlated with CD4 + T cells, cancer-associated fibroblast (CAF) and regulatory T cells (Tregs) in many tumors." (PMID 37620924, 2023). "Four of the 11 affected genes were associated with different cancer types: MUC6 and ZNF717 (prostate), SPEN (breast), and STK33 (pancreas)." (PMID 33968136, 2021). "No other recurrent somatic mutations were found in the pure IDP cohort; however, single cases had known cancer hotspot mutations in ERBB3 and HRAS, and a missense mutation in SPEN." (PMID 32195332, 2020). "This included E74 like ETS transcription factor 3 (ELF3), spen family transcriptional repressor (SPEN) and notch receptor 3 (NOTCH3) that are known to be mutated in various cancers." (PMID 31438645, 2019).
cancer (continued). "Three genes with mutations were known cancer associated genes (BAP1, ARHGAP35 and SPEN), but they were mutated in a single sample each, and were missense variants with uncertain functional effects." (PMID 27494029, 2016). "Although more and more studies demonstrated that the occurrence of SPEN mutations is very high in cancer, there have been no comprehensive pan-cancer studies on SPEN mutation." (PMID 37620924, 2023). "Then, the TIMER2.0 database was applied to explore the potential relationship between the SPEN expression and infiltration level of immune cells, including natural killer T cells (NKT), CD4 + T cells, cancer-associated fibroblast (CAF) and regulatory T cells (Tregs)." (PMID 37620924, 2023). "The genetic alterations of SPEN were analyzed in the TCGA pan-cancer cohort." (PMID 37620924, 2023). "Thus, we firstly analyzed the potential role of SPEN in the TCGA pan-cancer cohort and clinical samples." (PMID 37620924, 2023). "Third, the multivariate Cox regression analysis was performed, and we found that SPEN mutation was independent of cancer type in predicting prognosis." (PMID 37620924, 2023). "The remaining most frequent mutated cancer driver genes found in early-stage samples (KMT2C, ALK, BRCA2, GRM, ATM, and BRCA1) were not among those found to be the most frequently shared in late-stage samples (MUC16, CSMD3, KNT2C, NF1, LRP1B, SPEN, and TRRAP)." (PMID 37446001, 2023). "Bioinformatics analysis and immunohistochemistry (IHC) staining confirm that the expression of SPEN is significantly different in various cancers and may involve RNA splicing and processing via enrichment analysis." (PMID 37620924, 2023). "Additionally, differences were observed in NR3C2, ATR, ALK, EPHB6, SPEN in intermediate cells (I-1 to I-8) relative to the cancer cells." (PMID 35951662, 2022). "Three frameshift mutations in cancer genes were lost in the PDX tumors: HGF, SPEN, and PIK3CG." (PMID 33602919, 2021). "RBM15 is a member of the SPEN (split‐end) family of proteins, which interacts with RNA by binding with spliceosome components, playing vital roles in the mechanism of mRNA methylation as a m6A methyltransferase ‘writer’,37 and exerting oncogenic role in cancer." (PMID 36181462, 2023). "Notably, two trunk genes (SPEN and ITK), a branch gene (SMARCE1), and several private genes (FAT4, CACNA1D, ATR, RUNX1T1, TERT, and SRGAP3) were defined as cancer-associated genes, according to the cancer gene census." (PMID 28716121, 2017). "SPEN, mainly involved in X chromosome inactivation (XCI), plays an essential in tumorigenesis and sex differences in cancer." (PMID 37620924, 2023). "Two of the cancer gene products in the proximity proteome are known to physically interact with the N-CoR complex (SMARCE1 and SPEN)—suggesting these may all operate through a similar mechanism." (PMID 39767807, 2024). "Thus, the relationship of SPEN expression with Stromal, Immune, and ESTIMATE score was investigated in pan-cancers." (PMID 37620924, 2023). "In addition, SPEN expression significantly affected MMR gene expression in almost all cancer, and patients with SPEN mutant cancer harbored more MMR mutant genes." (PMID 37620924, 2023). "MSIsensor and MSI MANTIS scores in patients with SPEN mutant cancer were significantly higher than the patient with SPEN non-mutant cancer (P < 0.0001)." (PMID 37620924, 2023). "Moreover, SPEN expression significantly correlated with Immune Checkpoints, TMB, MSI and MMR in various cancers." (PMID 37620924, 2023). "Based on the mutation profiles in three genes (ROS1, SPEN, and PTPRT), we defined the TMB prognostic score that could predict cancer survival prognosis in the immunotherapy setting but not in the non-immunotherapy setting." (PMID 36911742, 2023).
cancer (continued). "Thus, the potential relationship between SPEN and MMR needs to be investigated in pan-cancer." (PMID 37620924, 2023). "The patients with SPEN mutant cancer (median, 19.63; interquartile range, 5.3–49.86) had higher TMB than patients without SPEN mutant cancer (1.9, 0.9–4.1; P < 0.0001) in the TCGA cohort." (PMID 37620924, 2023).
epithelial neoplasms of the (1 paper, 2024). "Interestingly, mutations in SPEN, a transcriptional suppressor, have been previously reported in epithelial neoplasms of the breast, colon, ovary, and nasopharynx." (PMID 39337668, 2024).
neurodevelopmental disorder (1 paper, 2023). A behavioral and cognitive disorder with onset during the developmental period that involves impaired or aberrant development of intellectual, motor, or social functions. "The gene SPEN (chr1:15.8–15.9(hg18), 16.1–16.2(hg19)) recently published as causing neurodevelopmental disorder was deleted in only two patients in our cohort (del68 and del54) both sharing deletion of long segments (including MOR3 or MOR4, respectively)." (PMID 36369750, 2023). "Other genes may contribute to the phenotype such as SPEN for which haploinsufficiency has been recently associated with neurodevelopmental disorders." (PMID 36369750, 2023).
SPEN also shares sentences with these, for which no sentence is quoted: acute myeloid leukemia (2 papers); diffuse large B-cell lymphoma (2); Intellectual disability (2); pancreatic cancer (2); prostate carcinoma (2); anaplastic oligoastrocytoma (1); Anxiety (1); asthma (1); atrioventricular block (1); B-cell lymphomas (1); bladder cancer (1); Bradycardia (1); carcinoma in situ (1); cardiomyopathy (1); cervical cancer (1); Chronic Lymphocytic Leukemia (1); colon adenocarcinoma (1); colon cancer (1); colorectal adenocarcinoma (1); dementia (1); endometrial cancer (1); esophageal cancer (1); Fanconi anemia (1); follicular lymphoma (1); glioma (1); Hepatic fibrosis (1); infection (1); left ventricular noncompaction (1); lung carcinoma (1); lymph node metastasis (1).
A further 11 diseases each share a sentence with SPEN in 1 paper.